RNU6-955P (RNA, U6 small nuclear 955, pseudogene)
Gene: Small nuclear RNA gene on chromosome 17 (4,619,749 to 4,619,852, reverse strand). Ensembl gene ENSG00000222429.
Homologues: Orthologues: chimpanzee U6 (98% identical), guinea pig U6 (79% identical), dog U6 (76% identical), dog U6 (74% identical), dog U6 (70% identical), rat LOC120097204 (68% identical), mouse Gm55634 (63% identical). Paralogues in human: RNU6-949P (85% identical), RNU6-116P (84% identical), RNU6-1060P (83% identical), RNU6-1273P (83% identical), RNU6-140P (83% identical), RNU6-17P (83% identical), RNU6-18P (83% identical), RNU6-19P (83% identical), RNU6-24P (83% identical), RNU6-33P (83% identical), RNU6-790P (83% identical), RNU6-1 (82% identical), and 1286 more.